TET2 (tet methylcytosine dioxygenase 2)
Diseases named in the same sentence as TET2 in open-access papers (continued):
Sharing a sentence is not in itself a finding about the gene and the disease.
Immunodeficiency (7 papers, 2018 to 2024). Failure of the immune system to protect the body adequately from infection, due to the absence or insufficiency of some component process or substance. "In another study, patients homozygous for LoF TET2 variants showed severe immunodeficiency, lymphadenopathy, hepatosplenomegaly, developmental delay, autoimmunity, and B-cell or T-cell lymphoma." (PMID 36814905, 2023). "In contrast, homozygous LoF variants of TET2 result in drastic alterations in early life that lead to extreme immunodeficiency." (PMID 36814905, 2023). "Similarly, exploring the molecular basis of TET2-associated immunodeficiency and TBRS, both of which are strongly linked to increased risk of hematopoietic malignancy, will help to elucidate the roles of TET2 and DNMT3A mutations as drivers of cancer." (PMID 36814905, 2023). "TET2 has various mechanisms in neoplastic and immune diseases and downregulates the expression of inflammatory cytokines IL-6 and IL-1β through recruiting HDAC enzymes for histone deacetylation in innate myeloid cells and macrophages." (PMID 39659792, 2024).
myocardial infarction (7 papers, 2013 to 2026). Gross necrosis of the myocardium, as a result of interruption of the blood supply to the area, as in coronary thrombosis. "8,9 Taken together, these findings suggest that CHIP, at least mediated by mutations in the most prevalent driver genes DNMT3A and TET2, may contribute to the development of CHF in patients after myocardial infarction." (PMID 30566180, 2019). "In 1 case of myocardial infarction information about TET2 mutation was not available." (PMID 23781511, 2013).
periodontitis (7 papers, 2017 to 2025). An acute or chronic inflammatory process that affects the tissues that surround and support the teeth. "The TET2 AA and AC genotypes have been reported to be associated with periodontitis." (PMID 40599550, 2025). "The proportion of TET2 positive cells was larger in periodontitis lesions compared to gingivitis lesions." (PMID 29201597, 2017). "Therefore, this increase in TET2 together with unchanged 5hmC levels may indicate a higher demethylation activity in periodontitis lesions." (PMID 29201597, 2017). "Other studies have explored the methylation levels of other potential targets, such as IL6 and tet-methylcytosine dioxygenase 2 (TET2) enzymes, and observed partial methylation of periodontitis tissues with increased levels of gene expression." (PMID 36291079, 2022). "Thus, smokers appear to present with downregulated DNA methylation levels in inflamed gingival tissues as opposed to non‐smokers, while TET2 levels in periodontitis lesions seem to be unaffected by smoking status." (PMID 35766184, 2022).
primary myelofibrosis (7 papers, 2016 to 2022). Myelofibrosis with myeloid metaplasia is a myeloproliferative disease with annual incidence of approximately 1 case per 100,000 individuals and age at diagnosis around 60 (an increased prevalence is noted in Ashkenazi Jews). "IDH1 and TET2 frequencies were 5% in essential thrombocythemia (ET) and 1.7% in ET and 5% in primary myelofibrosis (PMF), respectively." (PMID 28218607, 2017). "Our previous study (unpublished data) showed that there was a high frequency distribution in rs3733609 C/T genotype at Ten-Eleven Translocation 2 (TET2) locus in one Chinese familial primary myelofibrosis." (PMID 26843622, 2016). "Gene mutations in epigenetic regulators (ASXL1, TET2, DNMT3A and EZH2) and RNA splicing (U2AF1 and SRSF2) were considered as the additional subclonal mutations and cooperated with the MPN driver mutation (JAK2, MPL or CALR) to play a key role in the pathogenesis of primary myelofibrosis." (PMID 35740649, 2022).
T-cell acute lymphoblastic leukemia (7 papers, 2019 to 2025). Acute lymphoblastic leukemia of T-cell origin. "T-cell acute lymphoblastic leukaemia (T-ALL) exhibits exceptionally high levels of DNA methylation, with silencing of the DNA demethylating enzyme TET2 implicated in T-ALL’s hypermethylation phenotype." (PMID 40611304, 2025). "Interestingly, AzaC treatment also restores TET2 expression and hmdC in a different leukemic context (T-cell acute lymphoblastic leukemia), which results in rapid cell death, suggesting that TET activity is an important factor for the efficiency of AzaC or AzadC treatment in inducing cell death." (PMID 36089606, 2022).
acute kidney injury (6 papers, 2020 to 2025). Sudden and sustained deterioration of the kidney function characterized by decreased glomerular filtration rate, increased serum creatinine or oliguria. "TET2 was consistently demonstrated to play an important role in both cisplatin-induced and ischemia reperfusion-induced acute kidney injury." (PMID 38881848, 2024). "Epigenetic alterations are related to acute kidney injury-to-chronic kidney disease transition, and the roles of DNMT3A, TET2, and ASXL-1 in kidneys are reported." (PMID 37928907, 2023). "Our findings suggest that Tet2 may be a potential target for the intervention of IR-induced acute kidney injury (AKI)." (PMID 32616016, 2020).
acute leukemia (6 papers, 2019 to 2026). A clonal (malignant) hematopoietic disorder with an acute onset, affecting the bone marrow and the peripheral blood. "Co-mutations varied by subtype; MDS/MPN, NOS, and CMML cases frequently harbored mutations in epigenetic regulators (ASXL1, TET2) and splicing factors (SF3B1, SRSF2, ZRSR2), while acute leukemia cases showed alterations in JAK3, STAT3, and NRAS." (PMID 40806796, 2025). "However, TET2- and DNMT3A KO mice responded differently to even the same cooperating mutations: when combined with Flt3ITD mutation, TET2 KO mice died more rapidly of mostly MPNs, while DNMT3A KO mice survived longer but eventually developed mixed phenotype acute leukemia." (PMID 36675240, 2023).
brain tumors (6 papers, 2017 to 2023). "TET2 expression also decreases with increasing brain tumour grade, and lower TET2 expression has been associated with worse overall survival." (PMID 36050369, 2022). "To study the possible aberrant epigenetic regulation of TET2 in brain tumors, we first used data from the 450K Infinium Illumina methylation platform." (PMID 29899831, 2018). "In contrast, expression of TET2 and TET1 was generally higher (e.g. 2.37-fold for BXD-1425EPN and 4.14-fold for DKFZ-EP1NS cells for TET2) in the brain tumour cell lines compared with HeLa cells." (PMID 28228863, 2017).
chronic kidney disease (6 papers, 2020 to 2025). Impairment of the renal function secondary to chronic kidney damage persisting for three or more months. "In any case, no studies have been carried out on model animals deficient in TET2 or DNMT3a with chronic kidney disease in order to discern whether the mutations of each gene separately have a different effect on the atherogenic risk in this population." (PMID 37763205, 2023). "However, the impact of hematopoietic TET2 mutation on the risk of acute or chronic kidney diseases in elder people is still unclear." (PMID 32616016, 2020). "Subsequently, in vivo knockdown of TET2 significantly exacerbated VC in both vitamin D3– and adenine diet–induced chronic kidney disease (CKD) mouse models." (PMID 40067382, 2025). "Interestingly, other studies in chronic kidney disease also observed increased TET2 expression." (PMID 37091852, 2023). "The other interesting alternatively spliced genes were engaged in chemical carcinogenesis (ARAF), chronic kidney disease (NEK8) and kidney development (CNTRL, TET2, NLE1)." (PMID 38074096, 2023).
chronic myeloid leukemia (6 papers, 2021 to 2025). "For example, pathogenic or likely pathogenic alleles in GATA2, ASXL1, or TET2 were found in 10% of pediatric chronic myeloid leukemia cases, with additional putative risk alleles in another 60%." (PMID 41010648, 2025).
endometriosis (6 papers, 2018 to 2026). The growth of functional endometrial tissue in anatomic sites outside the uterine body. "Recent studies have shown a relationship between decreased levels of miRNA22-5p and increased expression of the TET2 gene in the endometrium during the implantation window in patients with endometriosis." (PMID 35409163, 2022). "TET2 protein levels were significantly higher in endometrium from women with minimal/mild endometriosis than in normal endometrium as indicated by western blot results." (PMID 32658928, 2020). "Based on a comprehensive analysis of minimal/mild endometriosis patients, we found that TET2 is upregulated in the endometrium during implantation window, and is directly affected by the miR22-5p level." (PMID 32658928, 2020). "Immunohistochemistry revealed that TET2 was strongly expressed in both the nucleus and the cytoplasm of epithelial and stromal cells of eutopic endometrium of endometriosis, whereas normal endometrium exhibited weak to moderate expression." (PMID 32658928, 2020). "We first established that miR22-5p expression decreased and TET2 expression increased in minimal/mild endometriosis during implantation window." (PMID 32658928, 2020). "However, how TET2 affects minimal/mild endometriosis-related infertility and the specific mechanism are unknown." (PMID 32658928, 2020). "MiR22-5p, which has not been thoroughly studied in endometriosis to date, directly dysregulated the expression of TET2, which is a key marker for DNA hydroxymethylation." (PMID 32658928, 2020). "Compared to endometrium from women without endometriosis, TET2 expression was significantly higher in endometrium from women with minimal/mild endometriosis during the secretory phase." (PMID 32658928, 2020). "MiR22-5p and TET2 expression in the mid-luteal endometrium from women with or without minimal/mild endometriosis was analyzed." (PMID 32658928, 2020). "The aim of the present study was to evaluate miR22-5p expression and the relationship between miR22-5p and TET2 expression in mid-luteal eutopic endometrium of infertile women with and without minimal/mild endometriosis using tissues and primary ESCs." (PMID 32658928, 2020). "Ten–eleven translocation genes (TET1, TET2, and TET3) are downregulated in endometriosis." (PMID 29743986, 2018). "Along those lines, endometriosis tissues have decrease expression of ten-eleven translocation genes (TET1, TET2, and TET3), which convert 5-methylcytosine to 5-hydroxymethlcytosine and play a role in changes in levels of 5-hydroxymethylcytosine marks in endometriosis tissues and blood." (PMID 30087267, 2018). "However, this study only focused on that miR22-5p dysregulates directly the expression of TET2 in the eutopic endometrium of endometriosis without the exploration of specific functions of miR22-5p." (PMID 32658928, 2020).
endothelial dysfunction (6 papers, 2017 to 2026). In vascular diseases, endothelial dysfunction is a systemic pathological state of the endothelium (the inner lining of blood vessels) and can be broadly defined as an imbalance between vasodilating and vasoconstricting substances produced by (or acting on) the endothelium. "TET2 may become a novel therapeutic target for endothelial dysfunction-associated vascular diseases." (PMID 28798687, 2017). "Changes in the expression of TET2 were shown to regulate autophagic activity in endothelial cell cultures, with the knockdown of Tet2 being accompanied by decreased expression of endothelial NO-synthase and increased expression of endothelin-1 as a typical hallmark of endothelial dysfunction." (PMID 36355225, 2022). "TET2 overexpression was also shown to decrease the expression of pro-inflammatory molecules involved in endothelial dysfunction, such as ICAM-1, VCAM-1 and MCP-1." (PMID 40072106, 2025). "Tet2-mediated hydroxymethylation inhibits oxidized LDL-induced endothelial dysfunction; therefore, TET2 protein is anti-atherosclerotic." (PMID 34440357, 2021). "This is the first report to show that TET2 improves oxLDL-induced endothelial dysfunction through the CSE/H2S/NF-κB pathway." (PMID 28798687, 2017). "The hypermethylated state and associated endothelial dysfunction observed in ECs, upon exposure to disturbed flow, may also be attributed to the downregulation of TET enzymes, particularly TET2." (PMID 40072106, 2025). "However, the relationship between TET2 and the CSE/H2S system and its role in endothelial dysfunction remain unclear." (PMID 28798687, 2017).
esophageal cancer (6 papers, 2015 to 2024). A primary or metastatic malignant neoplasm involving the esophagus. "In esophageal cancer tissues, 5-hmC expression is associated with shorter overall survival and TET2 expression levels." (PMID 31602281, 2019). "Our current study found that esophageal cancer tissues expressed lower levels of 5-hmC and TET2 than did normal esophageal epithelium." (PMID 26093090, 2015).
gout (6 papers, 2023 to 2025). A condition characterized by painful swelling of the joints, which is caused by deposition of urate crystals. "Tet2-deficient macrophages have shown increased production of proinflammatory cytokines, particularly IL-1β, in murine models of gout and CVD, and TET2 mutations were associated with higher IL-1β levels in the TOPMed study." (PMID 40305610, 2025). "For mild immunological conditions involving CH like gout, TET2-mutant CH was detected as an increased risk factor for gout from exomic analysis of 177,824 individuals from the MGB Biobank and UK Biobank." (PMID 39682303, 2024). "Further, TET2-mutant CHIP is linked to an increased risk of incident gout." (PMID 38162500, 2023). "Clonal hematopoiesis of indeterminate potential (CHIP) is highly associated with gout prevalence, and TET methylcytosine dioxygenase 2 (TET2) is among the most frequently mutated genes in the CHIP cases based on the database from MGBB and UKB." (PMID 39935474, 2025). "This association is supported by the observation of heightened NLRP3-independent IL-1ß secretion from TET2 knockout macrophages in response to monosodium urate crystals in vitro, indicating a pathogenesis similar to that of gout." (PMID 38162500, 2023). "The study revealed that the TET2 mutant CHIP is associated with increased gout risk in humans and identified CHIP as an amplifier of NLRP3-dependent inflammatory responses to MSU crystals in gout patients." (PMID 41311848, 2025).
head and neck squamous cell carcinoma (6 papers, 2017 to 2025). A squamous cell carcinoma that arises from any of the following anatomic sites: lip and oral cavity, nasal cavity, paranasal sinuses, pharynx, larynx, and salivary glands. "Numerous other studies have also reported associations between low TET2 transcript levels and poor survival, including OS in head and neck squamous cell carcinoma (HNSCC) (HR [95% CI] = 1.96 [1.01–3.77], p = 0.044) and disease‐free survival in metastatic PCa (p < 0.001)." (PMID 40116537, 2025). "Similarly, in head neck squamous cell carcinoma, reduced expression of TET2 was associated with reduced 5-hmC levels, larger and more advanced tumours, and poorer prognosis." (PMID 36050369, 2022). "In the study of head and neck squamous cell carcinoma (HNSCC), metformin can also inhibit cell proliferation and migration by restoring the expression of the tumor suppressor gene Tet2." (PMID 38012545, 2023).
ischemic stroke (6 papers, 2021 to 2026). A stroke disorder caused by obstruction of blood flow to the brain, due to thrombotic (local blood clot formation) or embolic (due to a blood clot or other material traveling from another site) event. "In conclusion, the study provided genetic evidence that TET2 is strongly associated with an increased risk of ischemic stroke and poor functional recovery." (PMID 40093911, 2025). "TET2 was moderately associated with ischemic stroke (OR = 1.05, P = 0.03) and strongly associated with TIA (OR = 1.07, P = 0.01)." (PMID 40093911, 2025). "To assess if TET2 is associated with ischemic stroke recovery, we evaluated the effect of TET2 on 90‐day mRS." (PMID 40093911, 2025). "Specifically, it has been reported that individuals with mutations in the CH driver gene, TET2, display an increased risk of ischemic stroke." (PMID 39742155, 2024). "Since it has been reported that individuals with hematopoietic TET2 loss-of-function mutations have a higher risk of ischemic stroke, we used Tet2 as a test driver gene for our study." (PMID 39742155, 2024). "TET2 showed the strongest association with total and ischemic strokes, while both DNMT3A and TET2 were associated with an increased risk of hemorrhagic stroke." (PMID 38162500, 2023). "TET2 loss‐of‐function was associated with higher rates of ischemic stroke." (PMID 40093911, 2025). "Therefore, using Tet2 as a test driver gene mutation, the current study assessed the impact of CH on acute and subacute outcomes after experimental ischemic stroke." (PMID 39742155, 2024). "In this article, we studied the molecular importance of the interaction between TET2 and β2SP in the brain after ischemic stroke." (PMID 34799994, 2021). "In conclusion, findings from this study suggest that in experimental ischemic stroke, without confounding cardiovascular risk factors, Tet2-mediated CH leads to a modest improvement in neurological outcome during the subacute phase." (PMID 39742155, 2024). "In summary, our results suggest that β2SP could regulate the gene 5hmC by interacted with TET2 and will become a potential therapeutic target for ischemic stroke." (PMID 34799994, 2021). "Our data suggest that β2SP could regulate the gene 5hmC by interacting with TET2 and will become a potential therapeutic target for ischemic stroke." (PMID 34799994, 2021).